SEPTIN7P14 (septin 7 pseudogene 14)
Gene: Transcribed unprocessed pseudogene on chromosome 4 (119,457,968 to 119,461,864, forward strand). Ensembl gene ENSG00000245958.
Diseases named in the same sentence as SEPTIN7P14 in open-access papers:
SEPTIN7P14 is named in the same sentence as 1 disease in open-access papers, as found by Europe PMC text mining. Sharing a sentence is not in itself a finding about the gene and the disease.
SEPTIN7P14 shares sentences with these, for which no sentence is quoted: medulloblastoma (1 paper).